IL6 (interleukin 6)
Diseases named in the same sentence as IL6 in open-access papers (continued):
Sharing a sentence is not in itself a finding about the gene and the disease.
tumor (continued). "Further studies showed that low levels of MCPIP1 in ccRCC induce endothelial cell angiogenesis and that the lack of MCPIP1 RNase activity is responsible for the secretion of proangiogenic factors—VEGF, IL-8 and IL-6—by tumour cells." (PMID 31639017, 2019). "TGF-β in the TME of HCC promotes the Tim-3 expression on TAMs, subsequently enabling the activated TAMs to facilitate tumor growth and immune tolerance via NF-κB signaling and downstream IL-6 production." (PMID 31500650, 2019). "As part of the systemic inflammatory response to a tumour or from the tumour itself, inflammatory mediators are released, including interleukin-1 (IL-1), IL-6, tumour necrosis factor- (TNF-) α, and acute-phase reactants." (PMID 31781312, 2019). "In vitro functional studies using THP-1 derived macrophages revealed CD38 expression to be associated with the M1 state, characterized by CD80 expression and secretion of TNFα and IL-6, all of which contribute to the anti-tumor immune response." (PMID 31552039, 2019). "This is achieved by paracrine signaling from tumor cells to the stroma via secretion of cytokines, such as interleukin-6 (IL-6) and IL-8 (CXCL8), which promote invasion, neovascularization, and inflammatory responses." (PMID 30353166, 2019). "Since neutrophil-derived NE promotes cancer development, a genetic knockout of NE resulted in reduced tumor burden, delayed cancer progression, lower proliferation rate, lower angiogenesis, and decreased levels of IL-6 and TGF-β." (PMID 32039025, 2019). "Several studies have reported that higher circulating IL-6 levels were significantly correlated with CRC status, demonstrating associations with tumor size, stage, and metastasis." (PMID 31795177, 2019). "IL-6 is usually host-derived, but it can be secreted from tumor cells, including urothelial cancer cells." (PMID 30754663, 2019). "IL-6-induced M2 macrophages exert a pro-tumor function by promoting GC cell proliferation and migration." (PMID 31480382, 2019). "Within the tumor microenvironment, IL-6 signaling is generally considered a malevolent player, promoting tumor progression." (PMID 31130595, 2019). "Increases IFN-γ and higher numbers of tumor-infiltrating CD4+ lymphocytes.The generation of IL-6, IL-12, IL-23 and TNF-α in dendritic cells increases rapidly." (PMID 31083446, 2019). "The NF-κB signaling pathway induces the production of cytokines that regulate the immune response (e.g., TNFα, IL-1, IL-6, and IL-8) as well as adhesion molecules that lead to the recruitment of leukocytes into tumor sites." (PMID 31775797, 2019). "Elevation of miR-21 levels has been observed in MDSCs directly derived from BM cells that were stimulated with GM-CSF and IL-6, as well as MDSCs from tumor-bearing mice, and in vitro overexpression or inhibition of miR-21 in BM cells altered MDSC expansion." (PMID 31710308, 2019). "The IL-6/STAT3 signaling pathway has also been implicated as a link between inflammation and tumor development." (PMID 30832202, 2019). "These newly described CAFs are characterized with increased secretion of inflammatory mediators, particularly IL-6, and decreased expression of αSMA, in addition to their ability to promote tumor cell proliferation." (PMID 30832219, 2019). "Inflammatory cytokines produced by the tumor or adipose tissue such as IL-6, TNF-α, and interleukin-1 beta (IL-1β) contribute to lipolysis, fat oxidation, and decreased lipogenesis as well as browning of white adipose tissue (beige adipose tissue)." (PMID 31683709, 2019). "It has been shown that interleukin-6 (IL-6) stimulates the malignancy and proliferation of tumor cells." (PMID 31569687, 2019). "The tumor tissues derived from IL-6 shRNA-treated MDA-MB-231 cells showed decreased expression of pSTAT3, pERK, PI3K, and pAkt proteins." (PMID 31252615, 2019). "IL6 was demonstrated to both stimulate and reduce tumour cell proliferation and growth, inhibit apoptosis and enhance invasiveness and metastasis." (PMID 31066211, 2019).
tumor (continued). "Concurrently, IL-6 can shift the anti-tumor immune responses towards immunosuppression via recruitment of myeloid-derived suppressor cells (MDSCs) and expansion of FoxP3+ Tregs." (PMID 31684144, 2019). "There are also interactions within immunologic components; for example, IL-6 can promote Th17 cell differentiation, and Tregs can suppress the anti-tumor response of effector T cells." (PMID 30824840, 2019). "It was demonstrated that HSP72 and HSP105 expressed on the surface of tumor-derived EVs promoted DCs to produce high levels of pro-inflammatory cytokines (IL-6, PGE2, IL-1β, TNF-α) in a TLR2- and TLR-4–dependent manner." (PMID 31680949, 2019). "IL-6 is closely correlated with STAT3, and STAT3 plays a key role in cell proliferation and differentiation, so IL-6 can not only promote the development of inflammation but also accelerate the proliferation of normal cells and tumour cells." (PMID 30956980, 2019). "For instance, several investigations have shown that secretion of IL-6 induces survival and proliferation of cancer cells and accelerates tumor growth via paracrine and autocrine signaling." (PMID 31491033, 2019). "When the expression levels of cytokines were examined in mice treated with AOM/DSS, we found increased mRNA expression levels of IL-6, IL-11, and TNFα in tumor tissues from Tg-tRXRα mice." (PMID 30931933, 2019). "Neutrophils and other immune system cells secrete tumor growth-promoting factors, such as vascular endothelial growth factor, hepatocyte growth factor, interleukin 6, and interleukin 8, and the growth of tumor cells is stimulated." (PMID 30899617, 2019). "MDSCs are recruited into the tumor site by the malignant cells by increasing the level of various soluble factors including IL-6, GM-CSF, TGFβ, VEGF and chemokines such as CCL2 and CCL5, in the tumor microenvironment." (PMID 31231358, 2019). "Next, to analyze the immunological changes resulting from administration of the anti-cancer drug in the C57BL/6N mouse stocks, we evaluated the expressions of IL-1β, IL-6 and IL-10 gene isolated from tumor tissue by real-time PCR." (PMID 32257905, 2019). "Consistent with previous results, the frequencies of IL-10+ and IL-21+ CD4+ T cells and IL-10+ B cells in tumor-draining lymph nodes and tumor tissues from Il6−/− tumor-bearing mice were significantly decreased." (PMID 31300052, 2019). "Fearon and colleagues demonstrated that inflammation (IL-6) alters ketogenesis pathways in the liver, leading to glucocorticoid secretion, impaired anti-tumor immunity, and failure of immunotherapy (anti-PD-1/anti-PD-L1)." (PMID 31174326, 2019). "Several statistically significantly disturbed genes (IL6, GBA3, TMEM27) show contradictory expression change trend to expression changes described in the literature and associated with tumor progression and metastasis." (PMID 31150395, 2019). "In our experimental model, enhanced secretion of IL-1β, PGE2, TNF-α, and IL-6 occurs following CRC cells/LSECs crosstalk in a tumor LFA-1/LSEC ICAM-1 interaction dependent fashion." (PMID 31511625, 2019). "IL-6 is a multifunctional cytokine that promotes tumor cell proliferation, invasion, and metastasis; inhibits tumor cell apoptosis; and promotes blood vessel growth." (PMID 31832112, 2019). "Interleukin-6 (IL-6) and tumor necrosis factor-alpha (TNFα), which are involved in tumor-related inflammatory processes, are known to induce neutrophilia independently." (PMID 30917620, 2019). "IL-6 was the most significant cytokine in this study related to liver function, tumor characteristics, and OS of HCC patients." (PMID 30824840, 2019). "IL-6/IL-6R/gp130 pathway communicates between breast tumor and immune cells, resulting in tumor promotion and enriched effect on BCSCs." (PMID 30885232, 2019). "Previous therapeutic interventions against inflammatory cytokines such as IL-6 and IL-1β have failed in clinical trials despite their well-known role in tumor and metastasis promotion." (PMID 31007849, 2019).
tumor (continued). "Pro-inflammatory cytokines such as tumor necrosis factor (TNF)-α, interleukin (IL)-1β, and IL-6 are reported to participate in chronic inflammation of tumor microenvironment, thereby creating a favorable environment for tumor progression and metastasis." (PMID 31252615, 2019). "IL-6 is well known to regulate tumor growth in several malignancies through the IL-6 receptor (IL-6R) and glycoprotein 130 (gp130/CD130) and activates diverse signaling pathways including MAP Kinase, JAK/STAT, PI3K/AKT, etc.." (PMID 31547070, 2019). "Our results showed that under 3D co-culture conditions and tumor-bearing tissues, IL6 expression in A549RR group was higher than that of the other two groups before and after irradiation." (PMID 31417646, 2019). "Taken together, our data suggest that administration of Tocilizumab monotherapy to tumor bearing mice results in a reduction in tumor burden and IgM secretion, despite the presence of IL-6 from bone marrow stromal cells in the TME." (PMID 31164961, 2019). "Blocking IL-6 or Ly-6G showed reduced tumor burden than anti-PD-1 treatment in high IL17A lung tumors." (PMID 31921642, 2019). "These cells have a high expression of IL-6, which is responsible for tumor progression through IL-6-induced Signal transducer and activator of transcription 3 signalling." (PMID 31766571, 2019). "On one hand, IL‐10 as well as IL‐6 were confirmed as negative regulators for innate immune cells that destroy the immunity to tumor cells." (PMID 31222971, 2019). "CCA-cell-derived EVs can generate tumor stroma by modulating fibroblastic differentiation of mesenchymal stem cells (MSCs) and releasing proinflammatory factors, such as IL-6, which lead to CCA proliferation." (PMID 31450710, 2019). "A previous study reported that deletion of IL6 or TNFα in a mouse model of HCC accelerated tumor development." (PMID 31552039, 2019). "IL-6 has been implicated in many of the SASP-induced effects on surrounding cells, including epithelial-to-mesenchymal transitions, tumour progression and fibrinogenesis." (PMID 31160572, 2019). "Cytokines, such as tumor necrosis α (TNF-α), interleukin 1β (IL-1β), and interleukin 6 (IL-6), are also shown to correlate with tumor-promoting inflammation." (PMID 31380247, 2019). "The investigators blocked IL-6 in combination with CTLA-4 in mouse models which created significant tumor shrinkage beyond that seen in mice treated with anti-CTLA-4 antibodies alone." (PMID 31730012, 2019). "In a recent study, enhanced basal autophagy in CAFs facilitated the secretion of tumor-promoting factors, notably IL6 and IL8, in neck squamous cell carcinoma (HNSCC)." (PMID 31014370, 2019). "BMA secrete abundant IL-6, which induces the epithelial-mesenchymal transition in tumour cells via the JAK2/STAT3 pathway, and strengthens the metastatic potential of tumour cells via PI3K/AKT." (PMID 31334678, 2019). "For example, astragalus saponins, astragalus and angelica polysaccharides, ferulic acid, and Z-ligustilide are known to suppress expression of some tumor-promoting cytokines, such as IL-1β, IL-6, and TNF-α." (PMID 31781219, 2019). "The formation of osteolytic lesions is mediated by osteoclasts via the release of multiple osteoclastogenic factors from tumor cells (e.g., IL-1, IL-6, IL-11, PDGF, MIP1α, TNF, M-CFS, RANKL and PTHrP)." (PMID 30823602, 2019). "While we did not see any difference of TNF-α, IL-15, and IFN-γ secretion between the tumor and the adjacent healthy tissue, we showed a trend with a higher production of IL-6 in tumor." (PMID 31105699, 2019). "At 24 h post-LPS injection, hippocampal Il-6 remained reduced in tumor-bearing mice relative to tumor-free controls (t27 = 2.6, p < 0.05)." (PMID 30679700, 2019). "These cells have the potential to release a variety of tumor-promoting cytokines, such as IL-6 and mitogens." (PMID 31614860, 2019). "Here, stromal-derived SASP factor IL-6 recruited myeloid suppressor cells and blocked anti-tumor T-cell response." (PMID 31137607, 2019).
tumor (continued). "As it is well known that IL-6 acts as promoter of tumor development and metastasis by composing inflammatory environment." (PMID 31766991, 2019). "In comparison, ~ 900-fold higher IL-6 was measured in sera from MDA-231/shCtrl tumor-bearing mice (0.91 ± 0.15 ng/ml, upper left blue) or MDA-468/shCtrl tumor-bearing mice (0.89 ± 0.17 ng/ml, upper right blue)." (PMID 31014367, 2019). "CAFs secrete IL-6 in the tumor microenvironment, which contributes to an up-regulation of HK2 via the IL-6R." (PMID 31212816, 2019). "Among them, the nerve growth factor (NGF) and the brain-derived neurotrophic factor (BDNF) cause axonal chemoattraction, and IL-6, IL-8, IL1b, and CCL5 foster tumor-associated hyperalgesia." (PMID 30825056, 2019). "Tumor resection resolved these tumor-induced decreases in Il-6, except in the frontal cortex, where resection tended to decrease Il-6, much like that of tumor-bearing mice (p = 0.07)." (PMID 30679700, 2019). "It is a matter of fact that CAF share several features with tumor-associated MSC, including the expression FAP, ACTA2, VEGF-AA, and IL6." (PMID 30825056, 2019). "High levels of IL-6 or IL-8 in ESCC tumours correlated with advanced tumour progression and poor patient survival." (PMID 31324197, 2019). "We demonstrated ADAM12 and IL-6 levels to be unrelated to tumor burden, solidifying the value of these markers in assessing the activation status of stroma, as opposed to merely reflecting total tumor burden." (PMID 31207904, 2019). "In the tumor-bearing mice, IL-6, CCL4 and VEGF were increased by RT in the tumor-associated fat pad." (PMID 31752313, 2019). "M1-like macrophages existed in the CC tumor stroma with a declined expression of M1-like markers such as IL-6, TNF-α and iNOS and tendedto transfer to M2-like phenotype under the influence of tumor cells." (PMID 31284453, 2019). "This phenomenon was associated with increased production of TNF, IL-6, CSF-1, VEGF-A, and IL-8 by tumor cells, which contribute to the recruitment of macrophages and the polarization of M2-like macrophages." (PMID 31775797, 2019). "In a positive feedback loop, STAT3 subsequently transduces signals for all members of the IL-6 and IL-10 families, which leads to chronic amplification of pathways that support tumor growth." (PMID 31842362, 2019). "Later the same group has shown that oral administration 4MU (400 mg/kg daily) inhibited tumor growth, decreased IL-6 production in Kupffer cells, and reduced cell migration and angiogenesis in the HCC+TAA model." (PMID 31847129, 2019). "Overall, our work demonstrates that redaporfin-vascular PDT induces extensive tissue damage at the primary (irradiated) tumour, which triggers an acute local inflammation characterized by IL-6 expression and neutrophilia that attained a maximum 24 h post-PDT." (PMID 31906092, 2019). "Interleukins, such as IL-6 and tumor necrosis factor (TNF)-α, and tumor-associated factors can induce the increased expression of lnc-CHOP in mouse MDSCs." (PMID 31404149, 2019). "IL-6 increases expression of miR-let-7a, resulting in decreased expression of the tumour suppressor gene NF2 and subsequent STAT3 activation." (PMID 30819129, 2019). "In contrast, we demonstrate that inhibition of stromal TGFβR2 reduces IL‐6 production from cancer‐associated fibroblasts, resulting in a reduction of STAT3 activation in tumor cells and reversion of the immunosuppressive landscape." (PMID 31609088, 2019). "Purified PDATME DC produced markedly elevated TNFα, IL-6, and IL-10 in culture compared with splenic DC from tumor-bearing hosts." (PMID 30926808, 2019). "The induction of interleukin-6 (IL-6), IL-10 and colony stimulating factor 1 (CSF-1) contributes to the proliferation and invasion of tumor cells and thereby displays a pro-tumorigenic role." (PMID 31455032, 2019).
tumor (continued). "The involvement of TNF-α/NF-κB and IL6/Stat3 pathways in tumorigenesis have been confirmed in a series of mouse models of GI malignancy focusing on inflammatory network of the tumor microenvironment." (PMID 31100828, 2019). "We found a broad range of IL-6 and IL-8 expression in tumor regions, including staining within tumor cells and tumor associated stromal cells." (PMID 31781510, 2019). "The tumor of SPC-A-1 cells grew faster after treatment with IL-6 (p < 0.05), which was consistent with previous studies." (PMID 30805774, 2019). "The presence of the HPV was associated with increased inflammatory cytokines (IL-1, IL-6, IL-17, TGF-β, TNF-α, and NF-kB) and tumor progression." (PMID 30642295, 2019). "M1 macrophages are commonly regarded as tumor-suppressing immune cells that secrete proinflammatory cytokines such as IL-1, IL-6, IL-23, IFN-γ and IL-12 which activate cytotoxic T cells and NK cells to eliminate cancer cells." (PMID 30823602, 2019). "Tumor cells produce cancer-related inflammatory mediators, such as tumor necrosis factor-α, interleukin-3 (IL-3), and IL-6." (PMID 31286873, 2019). "Accordingly, ablation of the cognate IL-33 receptor St2 limits tumor growth, and reduces mast cell-dependent production and release of the macrophage-attracting factors Csf2, Ccl3, and Il6." (PMID 31227713, 2019). "For example, in resveratrol-treated mice the reduction in tumor size correlated with miR-101b and miR-455 upregulation, which in turn led to the downregulation of the target cytokines IL-6 and TNF-alpha." (PMID 30959836, 2019). "Microglia become activated in response to early tumor stimuli, such as IL-6, TGF-β, prostaglandin E2 (PGE2), ATP, and miRNAs, which leads to the release of various cytokines, growth factors, and MMPs." (PMID 31611871, 2019). "The expression of Th1 cytokines (IL-2, TNF, IFN-γ) and Th2 cytokines (IL-4, IL-5, IL-6, IL-10) were examined in frozen tumor tissues from 80 GC patients by ELISA." (PMID 31417548, 2019). "Within the cortical and trabecular bone, IL-6 was expressed in ~ 37% of cells in the trabecular bone of tumor-bearing mice injected with MDA-MB-231GFP/Luc2 cells alone." (PMID 30813947, 2019). "Beyond its well-known role in fibrosis, IL-6 mediates cross-talk between CAFs and tumor cells, and represents a key player in the growth and metastatic evolution of several epithelial tumors, such as head and neck SCC and esophageal SCC." (PMID 31739489, 2019). "MSCs are also able to promote tumor growth and metastasize through direct cell-to-cell contact or through their secreted exosomes, which are able to carry different molecules such as IL-6, TFG-β1, CCL2, and fibronectin, or miR-375, miR340 and miR-155." (PMID 31547627, 2019). "Specifically, TAMs secrete IL-6 to aid in tumor promotion, whereas, during tumor progression T-cells become the primary source of IL-6." (PMID 31174326, 2019). "STAT3-activating cytokines such as IL-6 and IL-10 are found in abundance within the tumor microenvironment." (PMID 31766350, 2019). "STAT3 phosphorylation is considered to be driven by inflammatory and immunosuppressive cytokines and growth factors produced by both tumor and tumor-infiltrating cells including IL-6, IL-10, or VEGF-A." (PMID 31781102, 2019). "In return, ECs protect tumour cells by releasing quite a number of growth and survival factors like interleukin-6 (IL-6)." (PMID 31565662, 2019). "The expression of IL-6 or IL-8 in tumour tissues positively correlates with tumour progression and poor survival." (PMID 31324197, 2019). "Tumour cell-secreted IL-6 and IL-8 impair the activity and function of NK cells via STAT3 signalling and contribute to oesophageal squamous cell carcinoma malignancy." (PMID 31324197, 2019). "The whole ecosystem of HNSCC comprises paracrine and local signalling and mutual crosstalk of cells in the local tumour microenvironment and distal signalling by IL-6 to other parts of the body, e.g., fat tissue, muscles and liver." (PMID 30925774, 2019).